MIR548AN (microRNA 548an)
Synonyms: hsa-mir-548an
Gene: MicroRNA gene on chromosome X (106,639,814 to 106,639,896, forward strand). Ensembl gene ENSG00000263515.
Homologues: Orthologues: chimpanzee MIR548AN (100% identical). Paralogues in human: MIR548AY (86% identical), MIR548Z (86% identical), MIR548AZ (84% identical), MIR548H3 (83% identical), MIR548X2 (82% identical), MIR548AA1 (78% identical), MIR548N (78% identical), MIR548AH (77% identical), MIR548K (77% identical), MIR548F3 (76% identical), MIR548F1 (75% identical), MIR548AX (73% identical), and 13 more.